INS (insulin)
Diseases named in the same sentence as INS in open-access papers (continued):
Sharing a sentence is not in itself a finding about the gene and the disease.
Insulin resistance (continued). "On the other hand, studies in a diabetic rat model or in mice revealed a reduction of insulin resistance and an enhanced insulin- action under short term (10 weeks) or acute treatment with VPA, respectively." (PMID 36274160, 2022). "Insulin resistance in most cases is diagnosed when compensatory mechanisms decline (i.e., insulin secretion from pancreatic β cells increases), at the stage of pre-diabetes or when full-blown type 2 diabetes is diagnosed." (PMID 35684107, 2022). "Insulin resistance has long been considered a major biochemical abnormality of MetS, as most MetS subjects exhibit impaired insulin action." (PMID 36358481, 2022). "Impaired insulin signaling in vascular tissues inhibits glucose uptake and induces vascular insulin resistance." (PMID 36012219, 2022). "The assessment of the homeostatic model HOMA-IR is used to assess the function of the pancreatic beta cells and IR (Insulin Resistance) based on the values obtained by measuring the levels of basal (fasting) glucose and insulin." (PMID 35628058, 2022). "In a double-blind clinical trial, the insulin resistance and the level of insulin in type 2 diabetic patients were significantly improved by RSV treatment." (PMID 35355720, 2022). "Fasting level and AUC of serum insulin in oGTT as well as homeostasis model assessment of insulin resistance (HOMA-IR) were higher in IL-11−/− mice." (PMID 36424386, 2022). "These components of RAAS can cause oxidative stress in pancreatic β‐cells, which decrease insulin secretion and exacerbate insulin resistance." (PMID 36470584, 2022). "Numerous bodies of evidence reported that MO afforded blood-glucose-lowering effect through its activity either in increasing insulin secretion (insulin secretagogue) or improving insulin resistance." (PMID 35431967, 2022). "Circulating GLP-1 reaches pancreatic β cells and binds to GLP-1R, thus promoting the release of insulin, reducing insulin resistance and improving hepatic steatosis." (PMID 36119048, 2022). "One another important factor is insulin resistance, which is evidenced with elevation of insulin levels in PCOS group." (PMID 36212951, 2022). "Several abnormalities can predict insulin resistance, including impaired insulin activation of glycogen synthase, impairment of the proximal components of insulin signaling, and increased intramuscular triglyceride content." (PMID 36876056, 2022). "In this context, an overriding role has been attributed to insulin resistance and hyperinsulinemia and the renal effects of increased circulating insulin levels." (PMID 36289636, 2022). "The compacted model demonstrated that a greater proportion of HbA1c variance is explained when insulin resistance and insulin treatment were considered." (PMID 35052337, 2022). "In our previous review, we found that an asprosin-specific monoclonal antibody diminished circulating asprosin and enhanced insulin sensitivity in rats with insulin resistance." (PMID 35462799, 2022). "When insulin resistance develops in fat tissues, insulin-mediated inhibition of lipolysis is impaired." (PMID 35054972, 2022). "Contrasting data exist on what the principal molecular perturbations are which lead to insulin resistance, although it does involve the insulin signaling pathway, an integrated network of signaling proteins and secondary messengers." (PMID 35883605, 2022). "Studies have reported that adiponectin reduces insulin resistance in muscle and fat and improves insulin sensitivity." (PMID 36235638, 2022). "Leptin, fasting insulin, and insulin resistance each mediated between 20% and 50% of the total genetically predicted association of obesity with pre-eclampsia." (PMID 35104295, 2022). "They interfere with insulin signal transduction by participating in the insulin signaling pathway, leading to insulin resistance." (PMID 35056765, 2022).
Insulin resistance (continued). "Insulin resistance (IR) in insulin target tissues and pancreatic beta cell dysfunction, which leads to a relative deficiency in insulin secretion, are the main pathological features for the development of T2D." (PMID 35987697, 2022). "The increased glucocorticoid levels and the inhibition of melatonin under abnormal LD cycles affect blood glucose in various manners, including a decrease in insulin secretion, the exacerbation of insulin resistance and the expression of glucose transporters." (PMID 35008933, 2022). "Fractures are influenced by a complicated pathophysiological interplay between T2D parameters including a prolonged illness duration, diabetic complications, poor glycemic control, insulin resistance, and the use of insulin or oral antidiabetic medication." (PMID 36578954, 2022). "Insulin resistance is characterized by a decrease in tissue sensitivity to the effects of insulin, resulting in a compensatory increase in insulin secretion." (PMID 35736651, 2022). "Nevertheless, macrophages play a complex role, as their classical activation contributes to a pro-inflammatory phenotype, promoting the development of insulin resistance and type 2 diabetes, while their alternative activation improves insulin sensitivity." (PMID 35614088, 2022). "In other words, patients who require insulin, have higher insulin resistance thus higher inflammatory state." (PMID 35725489, 2022). "Those with severe VD deficiency had significantly higher blood pressure; fasting plasma insulin, the model for insulin resistance; HOMA-IR; triglycerides; cholesterol; and LDL than the two other groups." (PMID 36430854, 2022). "Insulin resistance is defined as the condition with attenuated insulin signaling in various tissues, particularly skeletal muscles, adipose tissues, and the liver, to elevate insulin secretion to make normoglycemia." (PMID 35054379, 2022). "T2D and other metabolic alterations derive from insulin resistance, i.e., the inability of insulin to activate a normal insulin response on its target cells." (PMID 36213259, 2022). "Following genistein administration, a significant decrease in insulin and glucose levels and insulin resistance were observed in rats with PCOS (p<0.001)." (PMID 34995042, 2022). "Improving insulin sensitivity or reversing insulin resistance is a potential treatment strategy for NAFLD." (PMID 36091227, 2022). "Here we show that mice with skeletal muscle-specific double knockout of Akt1/2, key downstream molecules of insulin signaling, serve as a model of premature sarcopenia with insulin resistance." (PMID 36198696, 2022). "GIRKO mice exhibit hallmarks of metabolic syndrome arising from insulin resistance: peripheral and central insulin resistance, elevated serum insulin, and elevated hepatic glucose production." (PMID 34801552, 2022). "It is known that catch-up growth as an abnormal developmental process can affect metabolisms in the body via inducing permanent changes in functions, reducing insulin sensitivity, or increasing circulating insulin levels, leading to insulin resistance." (PMID 35811949, 2022). "Brain insulin resistance is defined as the failure of cells to respond to insulin in the brain, resulting in dysfunction of synaptic, metabolic and immune response." (PMID 35992100, 2022). "A combination of two factors is involved in the T2DM etiology: inadequate insulin secretion by pancreatic β-cells and the inability of insulin-sensitive tissues to respond to insulin, namely, insulin resistance." (PMID 35956399, 2022). "Alongside ectopic fat deposition, an impaired response in the glucose lowering effect of insulin is often seen, referred to as systemic insulin resistance." (PMID 36295832, 2022). "The decrease in insulin sensitivity or the increase in insulin resistance is considered to be related to various metabolic diseases." (PMID 36501068, 2022).
Insulin resistance (continued). "Insulin resistance is created by chronic exposure to insulin or exposure to high levels of insulin, which desensitizes the receptor, resulting in the blocking of the insulin response." (PMID 35111361, 2022). "Yogurt treatment significantly prevented insulin resistance of H-fed mice as shown by higher GIR values in the Y group (p < 0.05), which was associated with a trend for higher insulin-suppressed hepatic glucose production (Ra) (p = 0.06)." (PMID 35292630, 2022). "Insulin resistance of the liver, adipose tissue, and skeletal muscle stimulates the secretion of insulin from the pancreas, which maintains a normal level of glycemia (pre-diabetic stage)." (PMID 35625904, 2022). "These intermediates activate protein kinase C isoforms that inhibit the insulin-signalling pathway, resulting in whole-body insulin resistance and the manifestation of T2DM." (PMID 35057577, 2022). "IL-1β is elevated in obesity and induces insulin resistance by inhibiting the insulin signaling pathway." (PMID 36230963, 2022). "Insulin-sensitive mice showed insulin resistance and glucose intolerance, whereas insulin-resistant mice showed near normalization of glucose tolerance and improved insulin sensitivity." (PMID 35832790, 2022). "The mice that specifically knock out the GLUT4 glucose transporter have decreased insulin sensitivity in the muscles and liver and increased serum glucose and insulin in mice, showing severe insulin resistance and glucose intolerance." (PMID 35242879, 2022). "Specifically, saturated fatty acids tend to increase insulin resistance, whereas long- and short-chain omega-3 fatty acids tend to enhance insulin sensitivity." (PMID 35267895, 2022). "The insulin resistance test is a valid and more reproducible test for assessing insulin sensitivity in experimental animals." (PMID 36109770, 2022). "We had previously established how Akt isoforms regulate AS160 in neuronal insulin signaling and insulin resistance." (PMID 36376971, 2022). "Because serum insulin and insulin resistance are often correlated with elevated circulating NEFA and TAG in adults, we assessed the effects of both age and CR on serum NEFA and TAG." (PMID 36315375, 2022). "Insulin resistance occurs in the presence of chronic energy excess, which leads to accumulation of ectopic lipids in hepatic and skeletal muscle tissue, impairing insulin signaling in these tissues, resulting in hyperglycemia." (PMID 36034454, 2022). "The following variables were analyzed: daily insulin requirement, insulin resistance, measurement of the cIMT, and levels of fetuin-A, E-selectin, and OPG." (PMID 36578961, 2022). "It has been shown that IL-6 has an important role in obesity and insulin resistance but also is cardinal in driving the beneficial effects of physical exercise in glucose and insulin sensitivity as well as body composition." (PMID 36387898, 2022). "On the other hand, Type 2 DM (T2DM) is a disease of insulin resistance; namely hyperglycemia persists despite the presence of high levels of circulating insulin." (PMID 36091180, 2022). "In the current study, compared with the HT group, the serum insulin concentration and insulin resistance index of the 0.4 mg/kg group were significantly reduced." (PMID 35405834, 2022). "As the liver is a vital organ in whole-body metabolic homeostasis, lipid burden in hepatocytes reduces insulin sensitivity and can lead to metabolic diseases, such as hepatic insulin resistance and type 2 diabetes (T2DM)." (PMID 35328400, 2022). "For instance, an increase in inflammation leads to modification of insulin signaling cascades, potentially contributing to insulin resistance." (PMID 35464026, 2022). "Because when insulin resistance occurs, the sensitivity of cells to insulin decreases significantly, which resulted in the elevation of the body's fasting plasma glucose level ultimately." (PMID 35811955, 2022).
Insulin resistance (continued). "Increased insulin resistance in the mother leads to increased insulin-mediated glucose and fatty acid levels, providing more energy sources for offspring." (PMID 35448667, 2022). "Chronic peripheral insulin increases and decreased brain insulin levels and activity are the hallmarks of insulin resistance." (PMID 36505102, 2022). "Overall, insulin resistance is multifaceted and involves cross-talk between the peripheral target tissues as well as various nodes within the insulin signaling pathway." (PMID 35883605, 2022). "These included glycated haemoglobin (HbA1), fasting blood glucose (FBG), post-prandial blood glucose, fasting insulin, postprandial insulin, and the homeostasis model-insulin resistance (HOMA-IR)." (PMID 35270573, 2022). "In this paper, we aimed to define normal values for insulin and the Homeostatic Model Assessment for Insulin Resistance (HOMA-IR) index based on a Brazilian cohort, and to suggest a new and simpler classification for MetS." (PMID 36160146, 2022). "Defective insulin autophosphorylation and reduced insulin receptor binding lead to insulin resistance." (PMID 35327342, 2022). "Based on the underlying mechanism, women with low beta cell function in combination with low insulin resistance are likely to benefit from insulin therapy." (PMID 35745174, 2022). "HOMA-IR (Homeostatic Model Assessment of Insulin Resistance) is the most widely used indicator for IR assessment, and it is calculated using plasma glucose and serum insulin levels." (PMID 35879737, 2022). "Consistent with improved glucose tolerance, genistein mice had lower fasting serum insulin and the homeostatic model assessment of insulin resistance (HOMA-IR) index, compared to HFD-fed mice." (PMID 36570152, 2022). "Insulin resistance is defined as the inability of cells to respond normally to the insulin, leading to a decrease in glucose uptake in primary insulin-sensitive organs such as skeletal muscle and adipose tissue." (PMID 35185804, 2022). "Elevated fasting blood glucose level, insulin, homeostatic model assessment for insulin resistance, and glycated hemoglobin product were observed to correlate with higher PAF burden (all trends p < 0.001)." (PMID 36211580, 2022). "High leptin level and leptin resistance can increase insulin level, promote insulin resistance, affect the insulin signal transduction pathway of hepatocytes, and increase fatty acid content in hepatocytes, resulting in fatty liver occurrence." (PMID 35069014, 2022). "d-allulose appeared to influence a greater decrease in insulin levels at 4 to 8 weeks compared to the other groups for the amelioration of insulin resistance." (PMID 35100325, 2022). "Mutant rodents also exhibited lower degrees of insulin resistance and, specifically, had better hepatic insulin sensitivity and glucose tolerance than wild types." (PMID 36140405, 2022). "It is described that vitamin D exerts its effects via the vitamin D responsive element (VDRE) signaling in the β pancreas cells, which improves the insulin secretion and insulin resistance via metabolic calcium signaling pathways." (PMID 35930297, 2022). "Increased insulin resistance and impaired insulin secretion have central roles in the pathophysiology of T2DM." (PMID 35432205, 2022). "Some mouse strains commonly used in T2DM research, such as C57BL/6J, develop insulin resistance on a high-fat diet and a subsequent upregulation of insulin secretion." (PMID 36260620, 2022). "For the same reason, the unnecessary use of insulin in patients with a preserved β-cell function should be discouraged, especially when a condition of insulin resistance is present." (PMID 35859794, 2022). "When oral drugs are not successful in modulating glucose and glycated hemoglobin (HbA1c) levels in people with insulin resistance or T2D, insulin can be utilized in monotherapy or together with various oral pharmacological agents." (PMID 35208257, 2022).
Insulin resistance (continued). "Insulin resistance is defined as a reduce response of insulin-target tissues, such as the liver, skeletal muscle, and visceral fat to insulin action." (PMID 36286282, 2022). "Type 2 diabetes is characterized by defective insulin secretion and/or insulin resistance, and the potential molecular mechanisms include interference of oxidative stress, insulin signaling, gluconeogenesis, and endoplasmic reticulum (ER) stress." (PMID 36438755, 2022). "The elevated NEFA levels induce insulin resistance and inhibit insulin’s antilipolytic action, which will increase the rate at which NEFA is released into the circulation." (PMID 36297569, 2022). "Insulin resistance (IR) is a condition that involves lower sensitivity to insulin in peripheral tissues, which directly leads to type 2 diabetes pathogenesis." (PMID 35684107, 2022). "ANGPTL-8 seems to play a supporting role in stimulating proliferation and increasing the pancreatic β-cell mass as well as improving glucose tolerance in insulin resistance, presumably by increasing insulin secretion." (PMID 35457182, 2022). "In recent years, most research efforts directed towards understanding insulin resistance have focused on potential defects in proximal steps of the canonical insulin signaling pathway." (PMID 36123369, 2022). "Evidence suggests that insulin resistance (i.e., low insulin sensitivity) is the major underpinning link between physical inactivity and MS." (PMID 35185617, 2022). "Insulin resistance refers to a phenomenon in which the biological effects of insulin in muscle tissue and the liver, such as promoting the production of muscle glycogen and liver glycogen, are reduced." (PMID 36248223, 2022). "Work with animal models has shown that betatrophin can facilitate the proliferation of β cells and insulin production during insulin resistance." (PMID 36295827, 2022). "In a diabetic rodent model, the supplementation of long-chain n-3 PUFAs also improved insulin resistance and glucose tolerance by increasing hepatic insulin sensitivity." (PMID 36297090, 2022). "Binding of lipopolysaccharide to the complex of CD14 and toll-like receptor 4 on the surface of innate immune cells, LPS can induce systemic inflammation, which ultimately impairs insulin sensitivity and induces insulin resistance-related metabolic disorders." (PMID 36093200, 2022). "The oral glucose tolerance test is an important tool to assess the release of insulin and insulin resistance in clinical and research areas." (PMID 35815262, 2022). "Evidently, ob/ob mice at 16 weeks have higher fasting serum insulin level and homeostasis model assessment of insulin resistance (HOMA-IR) value compared with lean mice, ponatinib treatment partially restored these abnormal increases." (PMID 36457708, 2022). "Antidiabetic mechanisms of action of quercetin are pleiotropic and involve reducing insulin resistance, promoting insulin secretion, as well as inhibiting glucose absorption in the small intestine and/or improving glucose utilization in peripheral tissues." (PMID 36245490, 2022). "Dysregulation of insulin signaling, resulting from various factors, is the main mechanism leading ultimately to insulin resistance." (PMID 35625904, 2022). "Decreased irisin secretion contributes to muscle insulin resistance, which was observed in high-fat-diet mice when the insulin action was significantly inhibited." (PMID 36552772, 2022). "Here, only a very short introduction to insulin signaling and the molecular basis of insulin resistance is provided." (PMID 35955975, 2022). "T2D is a disease characterized by insufficient production of insulin, excessive secretion of glucagon by pancreatic beta cells, and insulin resistance, resulting in impaired energy metabolism in the pancreas, liver, skeletal muscle, and other organs." (PMID 36009191, 2022). "During insulin resistance, β cells compensate for the dysfunction by increasing insulin demand through insulin secretion." (PMID 35745279, 2022).